INS (insulin)
Diseases named in the same sentence as INS in open-access papers (continued):
Sharing a sentence is not in itself a finding about the gene and the disease.
Hypoglycemia (continued). "The effects of DA on insulin secretion in vitro and the observed postprandial excursions support the hypothesis that gut-derived L-DOPA and DA delivered via the circulation impact insulin secretion and postprandial glucose levels, perhaps in defense against hypoglycemia." (PMID 30876866, 2019). "Thus, monitoring the trend of the glucose level and dosing adjustments of sulfonylurea, glinide, and insulin to prevent hypoglycemia are particularly crucial and may decrease the mortality risks in advanced DKD patients transitioning to dialysis." (PMID 30934740, 2019). "The main advantage of islet transplantation protocols over conventional insulin therapy is that transplanted islets are more efficient in maintaining normal blood glucose levels without producing excess insulin that could lead to episodes of hypoglycemia." (PMID 31561568, 2019). "In addition to the high-dose insulin induced hypoglycemia and 2-DG mediated glucopenia, we employed the hyperinsulinemic-hypoglycemic clamp technique to further validate the phenotype of an impaired hypoglycemia counterregulation in the Mc4rPVH-knockdown mice." (PMID 30503832, 2019). "A recent review by Turton and colleagues was unable to conclusively determine whether low vs. higher carbohydrate diets have significant effects on various T1D outcomes, such as HbA1c, total daily insulin, incidence of hypoglycaemia, and BMI, due to the large heterogeneity of the studies." (PMID 31067747, 2019). "The high incidence of hypoglycemia in this cohort may be primarily driven by the use of insulin pumps with integrated continuous glucose monitoring, as patients are able to see their glucose readings constantly and, therefore, notice and report more hypoglycemia." (PMID 31584770, 2019). "In addition, TRE, which is absorbed more slowly than GLU and other monosaccharides and other disaccharides, generally induces only a slight insulin response after being ingested; therefore, hypoglycemia is less likely to occur, even after the ingestion of a large amount of TRE." (PMID 31035710, 2019). "Finally, methods are classified as suspension algorithms if, instead of attenuating the basal insulin delivery, they simply interrupt basal insulin delivery when hypoglycemia is detected (detection-based suspension methods) or predicted (prediction-based suspension methods)." (PMID 30922295, 2019). "However, the proportion of time spent in hypoglycemia during the 2-days of CHO-loading was 10.4% and a lower insulin dose might have been required to reduce time spent in hypoglycemia." (PMID 31496994, 2019). "Moreover, severe neonatal hypoglycemia was lower compared to women on insulin alone." (PMID 31781670, 2019). "However, it is challenging to administer insulin into the brain because the peripheral administration may lead not only to hypoglycemia, but also to a very limited amount entering the brain." (PMID 31354415, 2019). "Furthermore, methadone co-occurring ADRs included ‘hyper-insulinemic hypoglycemia’ and ‘increased blood insulin’, which may indicate one of the mechanisms of the observed hypoglycemia ADR." (PMID 31462666, 2019). "We hypothesised that closed-loop insulin delivery would be safe and improve glycaemic control without increasing the risk of hypoglycaemia." (PMID 30935872, 2019). "Their insulin-independent mechanism of action inhibits sodium–glucose co-transporters, thus decreasing the renal glucose threshold (to ~ 100 mg/dL) and promoting urinary glucose excretion, without increasing the risk of hypoglycemia." (PMID 30819210, 2019). "Second, endogenously secreted insulin directly and rapidly acts on hepatocytes and suppresses postprandial glucose output from the liver, while subcutaneously injected insulin may exacerbate hypoglycemia due to exerting preferential actions on muscle and fat tissues." (PMID 30621663, 2019).
Hypoglycemia (continued). "When insulin levels are close to basal levels, such as when exercise is performed before breakfast, the risk of hypoglycemia is minimal and carbohydrate supplementation may not be required." (PMID 31258513, 2019). "Similarly, in this study, BB use was associated with hypoglycemia among basal insulin nonusers, but not among basal insulin users." (PMID 31775749, 2019). "Indeed, limitations of antidiabetic treatments, such as insulin and sulfonylureas, may include the onset of unpredictable symptomatic hypoglycaemia." (PMID 31513665, 2019). "Moreover, degludec offers the option for flexible timing of insulin doses, which, in addition to reducing patients’ fear of hypoglycemia, could also improve their adherence to treatment in the long term." (PMID 31397845, 2019). "Moreover, the risk of hypoglycemia and associated variations in glucose have been reported to be higher with the use of non-basal insulin, especially in patients with infection who have unstable diabetic foot complications." (PMID 30349614, 2018). "However, insulin treatment is not without its disadvantages, which are principally considered to be weight gain and the risk of hypoglycaemia." (PMID 29408938, 2018). "Increased insulin dose requirement might cause weight gain and hypoglycemia, which might lead to noncompliance with therapy and ultimately poor glycemic control." (PMID 29338714, 2018). "Basal insulin is a safe and easy way to obtain goal A1c without the risk of severe hypoglycemia." (PMID 31404422, 2018). "Consequently, the key element in effective insulin therapy is unremitting and frequent dosage adjustments that can overcome those dynamics and enable maintenance of optimal glycemic control while minimizing occurrences of hypoglycemia." (PMID 29682315, 2018). "Overall 21% of those with at least one episode of documented hypoglycaemia over the year had attended on another occasion with nausea without a documented diagnosis, in comparison to 5% of those without an episode of hypoglycaemia – and 22% vs 2% in those who were insulin-treated." (PMID 28918198, 2018). "Managing infants with NDM presents many problems, arising from the very small insulin doses required, the high risk of hypoglycemia, the lack of subcutaneous fat and the coordination of insulin therapy with the frequent and uncontrolled feeding schedule of the newborn period." (PMID 28943514, 2018). "However, in the case of an overdose of insulin or hypoglycaemic drugs, hypoglycaemia could also occur." (PMID 29587624, 2018). "AWRK6 presented no significant insulinotropic effect in Min6 cells without glucose, suggesting that AWRK6 could increase the insulin secretion under glucose response in β cells, with low risk for hypoglycemia under low glucose condition." (PMID 30301245, 2018). "However, this tuning also contains a high FP value that increases risk of hypoglycemia due to insulin administration without meal ingestion." (PMID 29547553, 2018). "The studies cited above showed that as compared to no action, significant reduction in insulin infusion at exercise onset is generally helpful in improving time spent with blood glucose levels in target ranges during exercise, but the risk of hypoglycemia remains largely present." (PMID 30713524, 2018). "Furthermore, our study showed that 91.6% T1DM patients with a previous severe hypoglycemia reported the reduction of insulin doses, a reaction that may compromise glycemic control." (PMID 30479669, 2018). "However, insulin degludec/insulin aspart 70/30 may be preferred over other premix insulin analogues considering lower incidence of overall and nocturnal hypoglycemia and superior FPG control when used." (PMID 29508275, 2018). "In addition, another mechanism recently described that may contribute to induce hypoglycemia in sepsis is an impairment in insulin clearence, also mediated at least in part, by LPS-TLR4." (PMID 29760586, 2018).
Hypoglycemia (continued). "In addition, it is important to note that there is possibility that insulin could be indirectly involved in steroidogenesis through insulin-induced hypoglycemia since hypoglycemia activates the HPA axis with the concomitant increase in corticosterone levels." (PMID 29567944, 2018). "This association between basal insulin and prandial GLP-1 receptor agonists is preferred today to the classical intensification of basal insulin therapy by adding prandial insulins, as it offers advantages of both a lower risk for hypoglycemia and a reduced weight gain." (PMID 30402500, 2018). "Importantly, higher dosage of insulin per day has not been shown to be associated with increased risk of hypoglycemia." (PMID 29682315, 2018). "However, IDegAsp may be preferred over premix insulin analogues in view of possible lower incidence of overall and nocturnal hypoglycemia and superior fasting plasma control." (PMID 29527102, 2018). "However, nocturnal hypoglycemia with basal insulin has emerged due to its features, and additional bolus insulin may be required to achieve near-normal glycemic levels." (PMID 30127860, 2018). "BCG treatment does not carry the risk of hypoglycemia as is the case for intense insulin therapy." (PMID 29951281, 2018). "Similarly, the addition of energy expenditure (measured by accelerometry) and galvanic skin response to a closed-loop system eliminated hypoglycemia, as insulin dosage decreased during exercise, even in the presence of increasing blood glucose levels during high intensity exercise." (PMID 30081478, 2018). "Importantly, mice with genetic deletion of IDE are viable; thus—unlike insulin—IDE inhibitors possess no intrinsic risk of triggering life-threatening hypoglycemia." (PMID 29447281, 2018). "This dynamic insulin therapy, first closes the gap between the initial prescribed total daily dose and the therapeutic one and then constantly evaluates each component of the therapy to fit the patient’s changing needs while preventing an increase in hypoglycemia." (PMID 29682315, 2018). "The absence of hypoglycemic events requiring assistance despite relatively tight glucose control may be due to the careful medical provider prescription management, especially rapid downward titration of insulin and sulfonylurea preventing hypoglycemia following dietary changes." (PMID 29417495, 2018). "Hence, the results observed during the maintenance phase (for this definition of hypoglycemia) could have been affected by the “learning” process of patients when using a new basal insulin." (PMID 29619381, 2018). "In addition, a patient's resistance to an injection regimen and fear of hypoglycemia could explain the particularly high rate of discontinuation among insulin initiators." (PMID 29713649, 2018). "In addition, knockdown of GLUT2 transporter in the hypothalamic area has shown to decrease feeding and body weight gain, suppress the insulin response triggered by intracarotid glucose injection and reduce the glucagon secretion in response to insulin-induced hypoglycemia." (PMID 32232085, 2018). "There was also one case report suggesting that the use of olanzapine during pregnancy was associated with neonatal hypoglycemia due to hyperinsulinemia unconfirmed in our cases where the glucose level was normal, while insulin levels had not been taken (not mandatory in the local protocol)." (PMID 28851326, 2017). "Closed-loop insulin delivery was safe both during and after unannounced exercise protocols in the in-hospital environment, maintaining glucose values mostly within the target range without an increased risk of hypoglycaemia." (PMID 28840263, 2017). "Automated insulin delivery options might also give women more confidence to administer larger pre-meal boluses, especially for the evening meal, with less fear of nocturnal hypoglycaemia." (PMID 28923465, 2017).
Hypoglycemia (continued). "However, this better glycemic control may be accompanied by undesirable effects, such as increased episodes of hypoglycemia need for larger and more frequent doses of insulin." (PMID 29218029, 2017). "Interestingly, further evidence has demonstrated that intensive insulin therapy significantly increases the risk of hypoglycemia and confers no overall mortality benefit among critically ill patients." (PMID 29215581, 2017). "However, in vivo induction of hypoglycemia by insulin, sulphonylureas or other agents may influence findings, as these agents per se impacts the effects of IR and IPC." (PMID 29121919, 2017). "In addition, as opposed insulin, continuous Ex4 treatment did not increase the risk of hypoglycemia when administered in a normoglycemic state." (PMID 29176623, 2017). "However, previous studies have reported that the association is predominantly in patients with spontaneous hypoglycemia while not on insulin therapy and at admission to hospital." (PMID 29233143, 2017). "However, the increase of Matsuda Index (insulin sensitivity) in male older patients compared to female older patients in our study might be related to the potential of nocturnal hypoglycemia in older male patients." (PMID 28271075, 2017). "In turn, patients may reflexively lower their insulin dose to prevent hypoglycemia." (PMID 28856166, 2017). "On the other hand, we recently reported that treatment with sitagliptin, a dipeptidyl peptidase-4 (DPP-4) inhibitor, attenuated the progression of carotid IMT in insulin-treated patients with T2DM compared with the conventional treatment without increasing the risk of hypoglycemia." (PMID 28250768, 2017). "The use of exogenous insulin which leads to supraphysiological peripheral insulin levels, in addition to the exercise-induced increase in muscle glucose uptake, predisposes to hypoglycaemia (e.g., dangerous fall in blood glucose levels, below the normal physiological range)." (PMID 28230765, 2017). "It was shown previously in mice that this hypoglycaemia cannot be explained by changes in insulin concentrations that are also reduced by LPS, but it could result from the increased glycolysis in muscles and immune cells, as well as from a reduced hepatic glucose production." (PMID 29273011, 2017). "Dramatic reductions in insulin requirements during the rewarming phase could lead to hypoglycemia and associated negative consequences such as poor neurologic outcome." (PMID 29075530, 2017). "However, this highlights that more careful blood glucose monitoring may be necessary in older patients receiving intensive insulin therapy, especially in men, to prevent the incidence of nocturnal hypoglycemia." (PMID 28271075, 2017). "Consequently, only metformin has been associated with reduced risk for prostate cancer, while oral hypoglycemia that directly affect insulin, have not." (PMID 27599544, 2016). "Moreover, this might also explain why acutely applied insulin detemir induces stronger effects on brain function than human insulin, and even amplify the impact of hypoglycemia in the CNS." (PMID 27589235, 2016). "Islet transplantation may make patients independent to external insulin, allowing them to not the pain associated with insulin injections, reducing hypoglycemia and the risks of end-organ damage, and improving QoL." (PMID 26990974, 2016). "As lack of insulin was associated with increased cryoinjury size observed in the diabetic mouse, we measured cryoinjury size in the control mice given insulin to induce hypoglycemia (glucose < 100 mg/dL)." (PMID 27034963, 2016). "Finally, the database did not provide key clinical information that would determine clinical decision making on types of insulin regimen such as body mass index (BMI), duration of disease, hypoglycemia inpatient admission, or useful days supply for insulin prescriptions." (PMID 26759271, 2016).
Hypoglycemia (continued). "This triple combination would be very effective in lowering HbA1c by different mechanisms – reduction of hepatic glucose production, improvement of insulin sensitivity and by the glucoretic effect – but not inducing any risk of hypoglycaemia and offering weight neutrality." (PMID 27071968, 2016). "However, when full-dose insulin pellets were administered beginning at day 32 day in an attempt to maintain relatively constant insulin dosing per gram of body weight as the animals grew, hypoglycemia ensued, which was fatal for several animals." (PMID 28702245, 2016). "Paliperidone may induce hypoglycemia by increasing insulin secretion." (PMID 27478670, 2016). "In addition, it may also be useful in the assessment of anterior pituitary function as shown by a significant copeptin stimulation following insulin induced hypoglycemia in a standard ITT." (PMID 26578365, 2016). "Normal suppression of endogenous insulin secretion, improved counterregulatory hormone responses, and increased endogenous glucose production, as well as decreased systemic and muscle glucose uptake all contribute to improving severe hypoglycemia in islet transplanted T1DM patients." (PMID 27047547, 2016). "Hypoglycemia may occur in patients who reactively bolus with correction insulin for an elevated 1 h postprandial blood glucose (bolus stacking) instead of adjusting mealtime bolus insulin (personal obs)." (PMID 27337958, 2016). "A risk for hypoglycemia might exist when linagliptin, as well as another DPP-4 inhibitor, is used as a treatment adjunctive to an insulin secretagogue, and an initial dose decrease in background secretagogue medication should be considered to prevent hypoglycemic events." (PMID 26075286, 2015). "As it is known that spontaneous hypoglycemia is correlated with higher mortality than hypoglycemia occurring during insulin administration, it would have been interesting to know whether the increase of severe hypoglycemia could be assigned to insulin administration." (PMID 26100120, 2015). "Metformin increases insulin sensitivity and decreases hepatic gluconeogenesis; it does not cause hypoglycemia and may lead to weight loss in some patients." (PMID 28702221, 2015). "Therefore, the increased serum IRI in patients with unexpected hypoglycemia could be considered endogenous and the hypoglycemic attacks might be due to IAb-insulin dissociation." (PMID 25961056, 2015). "Although we understood that it would be important to perform insulin tolerance test in order to reconfirm the dysfunction of the hypothalamus in this subject, we failed to obtain the agreement from this subject about the insulin load test due to the risk of the occurrence of hypoglycemia." (PMID 25918682, 2015). "The higher hypoglycemic episodes documented in our finding may be related to infrequent patient blood glucose and urine dipstick ketone monitoring to adjust insulin doses based on patient need that may lead to inadvertent use of insulin resulting in hypoglycemia." (PMID 26455633, 2015). "As the open-loop insulin pump, the previous insulin administration may lead to hypoglycemia." (PMID 26550021, 2015). "However, to balance long- and short-acting insulin administration, carbohydrate intake, as well as exercise intensity and duration is a crucial issue for type 1 diabetic subjects in order to avoid exercise-induced hypoglycemia." (PMID 26317981, 2015). "Convulsions may occur as a consequence of insulin-induced hypoglycemia." (PMID 25945273, 2015). "In multivariable-adjusted analyses, assistance from family members at the time of the insulin injection [presence/absence, OR (95% CI): 0.39 (0.16–0.97)] and drinking [current drinker/non- and ex-drinker, OR (95% CI): 4.89 (1.68–14.25)] affected mild hypoglycemia." (PMID 26102197, 2015).